MTOR (mechanistic target of rapamycin kinase)
Diseases named in the same sentence as MTOR in open-access papers (continued):
Sharing a sentence is not in itself a finding about the gene and the disease.
lung cancer (continued). "A recent study suggested that neferine can induce autophagy, ROS hyper-generation, PI3K/Akt/mTOR inhibition and cytotoxicity in lung cancer cells; however, the role of PI3K/AKT/mTOR inhibition on autophagy induction, as well as on the neferine-mediated cytotoxicity remains unclear." (PMID 25699594, 2015). "Furthermore, Akt and mTOR lie downstream of PI3K and increased mTOR phosphorylation is frequently observed alongside with activated Akt in NSCLC and dysregulation of mTOR contributes to lung cancer progression." (PMID 24533074, 2014). "Since SLC7A5 has been widely reported to activate the AKT/mTOR pathway, and the AKT/mTOR pathway has been found to regulate reactive oxygen species and protect cells from DNA damage, we speculated that the IGF2BP2-SLC7A5 loop may confer radioresistance on lung cancer through the AKT/mTOR pathway." (PMID 38281999, 2024). "In summary, in tumours derived from GBM, breast and lung cancers, regardless of the cellular origin or mutations carried, VDAC1 depletion led to similar metabolic reprogramming, including reversal of the cancer cell’s metabolic adaptation as controlled by the AMPK and mTOR signalling pathways." (PMID 30544833, 2018). "mTOR could act as an important regulator for 4E-BP1 phosphorylation, and p-4E-BP1 has been frequently found and/or indicated as a prognostic predictor for poor survival in different cancers such as breast cancer, nasopharyngeal carcinoma, hilar cholangiocarcinoma, gastric cancer, and lung cancer." (PMID 26360779, 2015). "In addition, 6-shogaol caused cell death through autophagy induction by the inhibition of the AKT/mTOR pathway in human NSCLC A549 cells and paclitaxel and feroniellin A exerted their cytotoxic effects by inducing both autophagy and apoptosis in human lung cancer A549 cells." (PMID 25490748, 2014). "The journal retracts the article titled “A Ferulic Acid Derivative FXS-3 Inhibits Proliferation and Metastasis of Human Lung Cancer A549 Cells via Positive JNK Signaling Pathway and Negative ERK/p38, AKT/mTOR and MEK/ERK Signaling Pathways”, as cited above." (PMID 40357647, 2025). "As expected, KAN0441571C induced dephosphorylation of ROR1 in a dose-dependent manner, as well as EGFR, SRC, PI3K110δ/AKT/mTOR (non-canonical Wnt pathway), and CREB in the NCI-H23 lung cancer cell line." (PMID 37111634, 2023). "Therefore, A. vera and A. emodin could be effective in lung cancer therapy by inhibiting cell proliferation, cytoskeleton activation, stimulated cell apoptosis as well as Cas‐3 and PKC activation, MAPK signalling, inhibition of ROS production, Akt/mTOR and PI3K/AKT pathways." (PMID 37697969, 2023). "Moreover, this study suggests that the activation of the mammalian target of rapamycin (mTOR)/CD1 pathway by p38 mitogen-activated protein kinase (MAPK) might be the approach for AR and epidermal growth factor receptor (EGFR) cross-talk, leading to lung cancer development." (PMID 35631448, 2022). "Collectively, these results demonstrate that PRMT5 promotes lung cancer cell proliferation through regulation of Akt activity, but not PTEN and mTOR signalling pathway." (PMID 30461193, 2019). "Our data show that the dual PI3K/mTOR inhibitor, BEZ235, is an effective antitumor agent for treating lung cancer in vitro and in vivo, regardless of EGFR status." (PMID 31262325, 2019). "Rapamycin, a well-established selective mTOR inhibitor, reactivates AKT via mammalian target of rapamycin complex 2 (mTORC2) signaling in several lung cancer cell lines, including A549, H358, and H460 but not HL-60 leukemia cells." (PMID 29295560, 2017). "Inhibition of the MEK/ERK, but not PI3K or mTOR, pathway reduced the expression of PDF and MAP1D in both colon and lung cancer cell lines." (PMID 23815882, 2013).
lung cancer (continued). "Estrogen receptor β (ERβ) is the primary ER subtype expressed in lung cancer; upon binding to estrogen in the cytoplasm, ERβ activates non-genomic signaling pathways, including PI3K/AKT/mTOR and RAS/RAF/MEK/MAPK pathways, promoting cancer cell proliferation and apoptosis evasion." (PMID 33585221, 2020). "Again, AMPKa downstream proteins, mTOR and ATG7, were not changed, indicating these two proteins may be not required for AMPKa regulation of autophagy in these lung cancer cells." (PMID 33312753, 2020). "Again, AMPKa downstream proteins, mTOR and ATG7, were not changed, indicating that these two proteins may be not required for AMPKa in regulating autophagy in these lung cancer cells." (PMID 33312753, 2020). "Additionally, PRMT5 promoted lung cancer cell proliferation through direct interaction with Akt and regulation of Akt activity, but not interaction with PTEN and mTOR." (PMID 30461193, 2019). "Although the mTOR phosphorylation, a key factor in protein synthesis, was not decreased by MAC, activation of Raptor, which consists of mTORC1 with mTOR, was decreased by MAC‐induction Raptor phosphorylation in lung cancer cells." (PMID 30338933, 2018). "In exactly the same way, rapamycin sensitized crizotinib-resistant EML4-ALK+ lung cancer cells to ALK inhibition: Crizotinib alone did not affect ALK and AKT activity, but blocked the feedback activation from mTOR to AKT, when administered together with rapamycin." (PMID 29755689, 2018). "We investigate whether the functional roles of CD164 promote lung tumor-initiation and drug resistance through the Akt/mTOR axis, as the clinical significance of CD164 expression in lung cancer has not been reported to date." (PMID 28903328, 2017). "Combined, but not individual, treatment of lung cancer cells strongly increased the phosphorylation of eIF2α S51, ATG13 S318, JNK and p38 whereas it decreased the phosphorylation of AKT T308, p70 S6K T389, mTOR S2448 and ULK-1 S757." (PMID 27903966, 2017).
prostate carcinoma (813 papers, 2006 to 2026). A carcinoma that arises from epithelial cells of the prostate gland. "Specifically, knockdown of the splice variant CD44v6 in prostate cancer cell lines enhanced chemo-/radiosensitivity by downregulation of the PI3K/AKT/mTOR and Wnt/β-catenin signalling pathways." (PMID 41168417, 2025). "The development and metastasis of prostate cancer are closely linked to the abnormal activation of the PTEN/AKT/mTOR pathway." (PMID 41343534, 2025). "Restoration of downstream mTOR signaling causes resistance to combined Akt and androgen receptor blockade in prostate cancer." (PMID 39919177, 2025). "Overall, our data show a significant decrease in prostate cancer cell survival and proliferation in association with inhibition of Akt-mTOR-p70 S6K and activation of sestrin-2-AMPK signaling with CA treatment." (PMID 38732504, 2024). "We observed promising effects against prostate cancer using the polyphenol resveratrol that were associated with inhibition of the Akt-mTOR and activation of the AMPK pathways." (PMID 38732504, 2024). "Dysregulation of the phosphatidylinositol 3-kinase (PI3K)/AKT (AKT serine/threonine kinase)/mammalian target of rapamycin (mTOR) signalling pathway is linked to the progression of prostate cancer." (PMID 38913213, 2024). "Hyperactivation of the PI3K/Akt/mTOR signaling pathway in prostate cancer is mostly related to mutations in PTEN; however, other abnormalities, such as gain-of-function mutations in PIK3CA or AKT genetic aberrations, have also been detected." (PMID 38672636, 2024). "We conclude that R26MTA1; Ptenf/f mice recapitulate key features of MTA1/mTOR signaling pathway activation-associated advanced prostate cancer and represent a useful model for exploring novel therapeutic approaches to manage advanced disease." (PMID 38611022, 2024). "In the present study we found that SphK1/2 dual inhibition by SKI-178 caused Akt-mTOR inactivation in prostate cancer cells." (PMID 37604912, 2023). "Different components of mTOR-associated complexes are modified in prostate cancer but usually in small frequencies." (PMID 36768610, 2023). "The PI3K-Akt-mTOR pathway has been implicated in prostate cancer development and progression and is deregulated in up to 50% of prostate cancers." (PMID 36029329, 2023). "Research has demonstrated that the PI3K/AKT/mTOR signaling pathway is linked to drug resistance in certain tumors, such as leukemia, prostate cancer, colon cancer, and lymphoma." (PMID 37152048, 2023). "Androgens stimulate mTOR activity in prostate cancer cells with PTEN deficiency by the upregulation of genes involved in nutrient availability and independently of PI3K/AKT activation." (PMID 36768610, 2023). "In one study, it was shown that miR-100-5p was expressed at lower levels in prostate cancer cells which was associated with increased expression of mTOR thereby affecting the proliferation, migration, and invasion of tumor cells." (PMID 36909201, 2023). "For example, BSN was reported to cause apoptosis by modulating the PI3K/Akt/mTOR cascade in prostate cancer cells." (PMID 36829581, 2023). "In accordance with our findings, nuclear mTOR has been found to be associated with the progression of different tumor types, such as prostate cancer and multiple myeloma." (PMID 37176048, 2023). "The PI3K/AKT/mTOR (PAM) signaling pathway is frequently mutated in prostate cancer and thus a good candidate for the involvement in tumor progression." (PMID 35252204, 2022). "For instance, higher nuclear mTOR expression has been associated with poor prognosis in endometrial, thyroid, and prostate cancers." (PMID 36077039, 2022). "EpCAM-regulated carcinogenesis was proved to be associated with PI3K/Akt/mTOR signaling pathway activation in animal experimentation on prostatic cancer." (PMID 35986321, 2022).
prostate carcinoma (continued). "Bufadienolide, a traditional Chinese drug Chan’Su-derived cardiac glycoside, caused G1 arrest of breast and prostate cancer cells by inhibiting insulin-like growth factor-I (IGF1)-activated phosphorylation of mTOR, S6K1, and 4EBP1." (PMID 36139919, 2022). "Due to PTEN depletion, PIK3CA amplification, and other genetic changes, the PI3K-Akt-mTOR pathway is most frequently overactivated in prostate cancer, which is associated with cancer progression, cancer metastasis, as well as development of drug resistance." (PMID 35296639, 2022). "In prostate cancer radioresistance is largely modulated by the PI3K/Akt/mTOR activation in association with an epithelial-mesenchymal transition (EMT)/cancer stem cell-like phenotype." (PMID 36172166, 2022). "Research by Yamamoto and colleagues showed that a single dose of sorafenib (30-60 mg/kg) decreased the activation of the PI3K/AKT/mTOR signaling axis in a mouse model of PTEN-deficient prostate cancer." (PMID 34026624, 2021). "A study of Piezo1 in prostate cancer showed that shRNA knockdown of Piezo1 significantly reduced proliferation and caused cell-cycle arrest by reducing the activity of Akt/mTOR in a calcium-mediated process." (PMID 34831037, 2021). "PTEN mutation is an important molecular subtype of poor prognosis of prostate cancer most strongly associated with aberrant mTOR activity due to effects on PI3-kinase/Akt signalling." (PMID 34725334, 2021). "Previous work has revealed that the dual PI3K/mTOR inhibitor dactolisib (BEZ235) promotes AR signaling in a HER2/3 dependent manner in PTEN-deficient prostate cancer models, while AR-targeted therapy augments AKT signaling." (PMID 33105713, 2020). "AMPK inhibits the mammalian target of rapamycin (mTOR) protein, which has been implicated in prostate cancer progression." (PMID 32056047, 2020). "To further minimize random errors to confirm the positive association between the mTOR rs2295080 polymorphism and the risk of urinary system tumors, prostate cancer, and leukemia, we performed FPRP analysis." (PMID 32597485, 2020). "We highlight the positive association between the TG genotype within the mTOR rs2295080 polymorphism and a reduced risk of urinary system tumors, especially prostate cancer, in the Chinese population." (PMID 32597485, 2020). "In fact, it was recently suggested that the acquisition of EMT and CSCs phenotypes is linked with the activation of PI3K/AKT/mTOR signaling in IR-resistant prostate cancer cells." (PMID 32197467, 2020). "For those molecules that were demonstrated to be correlated with poor prognosis in HNC patients, RHEB was also found overexpressed in prostate cancer, associated with poor prognosis, and promoted cell growth via the regulation of the mTOR signaling pathway." (PMID 33238517, 2020). "p19, p21 and p27 loss have also been detected in prostate cancer cells with acquired resistance towards the mTOR inhibitor everolimus." (PMID 31010254, 2019). "PTEN, a tumor suppressor gene acting as a negative regulator of the PI3K/AKT/mTOR pathway, frequently undergoes copy number loss as an early event in prostate cancer development and its loss is correlated with progression to castration-resistant disease." (PMID 31366128, 2019). "mTOR signaling is implicated in prostate cancer progression and androgen deprivation therapy resistance." (PMID 31608109, 2019). "Since overexpression of AKT/mTOR/S6K1 signaling pathway is closely linked with angiogenesis in prostate cancer, the effects of guava leaf hexane fraction on this pathway was observed." (PMID 31597327, 2019). "Chronic treatment of prostate cancer cells with another mTOR inhibitor, everolimus, has also been associated with increased metastatic activity." (PMID 30200497, 2018). "The PI3K/AKT/mTOR pathway is frequently activated in advanced prostate cancer, due to loss of the tumour suppressor PTEN, and is an important axis for drug development." (PMID 28915623, 2017).
prostate carcinoma (continued). "Induction of autophagy by an mTOR inhibitor increased prostate cancer cell susceptibility to irradiation." (PMID 29201078, 2017). "In prostate cancer cells, Akt-dependent regulation of NF-κB is controlled by mTOR and Raptor, in association with IKK." (PMID 28885545, 2017). "We demonstrated that GPRG6A is expressed in human prostate cancer cell lines and has an evolutionarily divergent polymorphism that does not affect cell surface expression but preferentially enhances mTOR signaling." (PMID 28659174, 2017). "Sphingosine kinase 1 (SK1) and phosphoinositide 3-kinase (PI3K)/Akt/mammalian target of rapamycin (mTOR) pathways have been implicated in prostate cancer chemoresistance." (PMID 27821815, 2016). "AMPK inhibits the mammalian target of rapamycin (mTOR) protein, which has been implicated in prostate cancer cell progression and is a current target of prostate cancer treatment." (PMID 26977321, 2016). "Recently, several researches have demonstrated that the activation of the PI3K/AKT/mTOR pathway was strongly implicated in the prostate cancer progression." (PMID 27713912, 2016). "mTOR activity has been associated to increased cell motility and metastasis in colorectal cancer, prostate cancer and lymphangioleiomyomatosis (LAM)." (PMID 27119232, 2016). "Immunohistochemistry analysis also reveals a strong association between mTOR-p70S6K activation and prostate cancer progression." (PMID 26447757, 2015). "Most important, we show that dual inhibition of AR and PI3K/mTOR signaling pathways has synergistic inhibitory effect of cell growth associated with increase of apoptosis in both castration-sensitive and resistant prostate cancer cells." (PMID 26506516, 2015). "MTOR SNPs are reported to be associated with susceptibility to GC, renal cell carcinoma, prostate cancer, and esophageal squamous cancer." (PMID 26317520, 2015). "Stratification analysis for associations between mTOR variants and prostate cancer risk by dominant genetic models in all subjects of Eastern Chinese men." (PMID 23940798, 2013). "In contrast, some greater FPRP values for the other significant associations between mTOR variants and prostate cancer risk suggested some possible bias in the findings, which need further validation in larger studies." (PMID 23940798, 2013). "Stratification analysis for associations between combined risk genotypes of mTOR variants and prostate cancer risk." (PMID 23940798, 2013). "Logistic regression analysis of associations between mTOR genotypes and prostate cancer risk in Eastern Chinese men." (PMID 23940798, 2013). "Considering that this novel axis is activated in both human colon and prostate cancer cells and transformed mouse fibroblasts, it is likely to represent a fundamental mechanism underlying mTOR signaling in cancers." (PMID 24244675, 2013). "Specifically, reciprocal interactions between the AKT/mTOR and AR pathways have been implicated in prostate cancer progression." (PMID 22614157, 2012). "A number of reports have implicated mTOR signaling as a prominent factor during prostate cancer progression." (PMID 22614157, 2012). "Metastatic potential of PC3 prostate cancer cells, susceptible (PC3par) or resistant (PC3res) to the mTOR-inhibitor RAD001 was investigated." (PMID 22782340, 2012). "Together, these data indicate that PTEN loss and aberrant mTOR signaling are intrinsic cellular properties associated with ridaforolimus sensitivity in prostate cancer lines." (PMID 22614157, 2012). "Analysis of tumour specimens has documented the association between mTOR variations and prostate cancer risk." (PMID 22782340, 2012). "A connection between decreased expressions of miR-99a, miR-99b and miR-100 and elevated level of mTOR was also described in prostate cancer and was associated with more advanced tumor stage." (PMID 22920721, 2012).